SIRT3 (sirtuin 3)
Diseases named in the same sentence as SIRT3 in open-access papers (continued):
Sharing a sentence is not in itself a finding about the gene and the disease.
intracerebral hemorrhage (7 papers, 2018 to 2024). A cerebrovascular disorder characterized by bleeding into one or both cerebral hemispheres including the basal ganglia and the cerebral cortex. "In intracerebral hemorrhage, the decline in SIRT3 levels is highly correlated with the severity of bleeding and poor prognosis at 90 days, suggesting that plasma SIRT3 can serve as a potential prognostic biomarker for intracerebral hemorrhage." (PMID 39091611, 2024). "Evidence suggests that intermittent fasting can decrease microglial activation and neuroinflammation following intracerebral haemorrhage in a SIRT3-dependent manner." (PMID 37009480, 2023). "A previous study demonstrated that Honokiol (an agonist of SIRT3) improved the oxidative stress injury in hyperglycemic rats after intracerebral hemorrhage (ICH)." (PMID 35923224, 2022). "In a model of intracerebral hemorrhage, the SIRT3 agonist Honokiol increased SIRT3 expression, promoted SOD deacetylation, and increased TFAM to protect mtDNA." (PMID 35936890, 2022). "Increasing evidence has shown that SIRT3 exerts neuroprotective effects against several types of brain damage, such as cerebral ischaemia/reperfusion (I/R) injury, subarachnoid haemorrhage (SAH), traumatic brain injury (TBI), and intracerebral haemorrhage (ICH)." (PMID 37009480, 2023). "Moreover, evidence is still lacking regarding the two-sided effect of SIRT3 in other types of brain injuries, such as subarachnoid haemorrhage, TBI, and intracerebral haemorrhage." (PMID 37009480, 2023).
lung adenocarcinoma (7 papers, 2017 to 2026). A carcinoma that arises from the lung and is characterized by the presence of malignant glandular epithelial cells. "The purpose of this study was to analyze the effect of SIRT3-mediated deacetylation of mitochondrial SLC25A22 on RAS-selective lethal 3 (RSL3)-induced ferroptosis in lung adenocarcinoma (LUAD)." (PMID 40298644, 2025). "Lung adenocarcinoma cells that were transfected/untransfected with SIRT3 overexpression lentiviral vectors were injected subcutaneously to assess the effect of SIRT3 overexpression on the ROS-FPR1/HIF-1α axis under hypoxic conditions." (PMID 37747648, 2023). "The TCGA database showed the same trend, in lung adenocarcinoma and lung squamous cell carcinoma, the expression level of Sirt3 in primary tumor was significantly higher than that in normal lung tissue adjacent to cancer." (PMID 34405009, 2021). "Previous results have indicated that Sirt3 acts as a tumor suppressor against lung adenocarcinoma tumor tumorigenesis by maintaining mitochondrial integrity and efficient oxidative metabolism." (PMID 28443025, 2017). "Recently, studies have shown that Sirt3 acts as a tumor suppressor in lung adenocarcinoma development and progression and may be a promising therapeutic target for lung adenocarcinoma." (PMID 28443025, 2017). "Here, we compared the proteomic and acetylomic responses of lung adenocarcinoma (A549) and breast adenocarcinoma (MCF7) cell lines to SIRT3 inhibition by 3-TYP." (PMID 41683751, 2026).
steatosis (7 papers, 2020 to 2026). Increased lipid within the cytoplasm of cells. "Previous studies have reported that Sirt3-deficient mice show accelerated steatosis compared to WT mice because of hyperacetylation and the subsequent reduced activity of mitochondrial metabolic enzymes such as long-chain acyl-CoA dehydrogenase (LCAD)." (PMID 32912335, 2020). "OTUD3 then stabilizes SIRT3 via deubiquitination, thereby inhibiting mtDNA oxidation and alleviating steatosis-induced metabolic disorders." (PMID 41640247, 2026). "In mouse studies, ablation of SIRT1 in the liver or global SIRT7 deletion led to fatty liver under standard diet conditions, and global SIRT3 ablation accelerated steatosis development under HFD." (PMID 35743232, 2022). "And DHM could effectively ameliorate PA-induced steatosis in hepatocytes through improving mitochondrial respiratory chain function and antioxidant capacity via SIRT3." (PMID 34503544, 2021). "This would suggest that increased fatty acid synthesis was not a key mechanism in the exacerbation of steatosis in Sirt3−/− mice fed the HFD." (PMID 32912335, 2020).
triple-negative breast carcinoma (7 papers, 2019 to 2025). An invasive breast carcinoma which is negative for expression of estrogen receptor (ER), progesterone receptor (PR), and human epidermal growth factor receptor 2 (HER2). "Thus, ADTL-SA1215 activates SIRT3 and leads to SIRT3-driven autophagy/mitochondrial autophagy-associated cell death in triple-negative breast cancer cells, with significant antiproliferative and antimigratory activities." (PMID 39479446, 2024). "This study offers insights for creating SIRT3 agonists to treat triple-negative breast cancer and suggests potential for treating other types of cancer as well." (PMID 38773972, 2024). "It has been observed that it can hinder the deacetylation activity of SIRT3, hence impeding the growth and spread of triple-negative breast cancer." (PMID 38773972, 2024). "ADTL-SA1215 also induced autophagy of MDA-MB-231 cells both in vitro and in vivo in a murine xenograft model of triple-negative breast cancer via Sirt3-mediated regulation of multiple autophagy-related proteins, confirming the efficacy of Sirt3 activation in this cancer model." (PMID 38474697, 2024). "Methods: wt and GLS1-silenced triple negative breast cancer spheroids were treated with 3-TYP, a selective SIRT3 inhibitor, and with MC3138, a new selective SIRT5 activator, both alone and in combination." (PMID 41599625, 2025). "Compound 3D enhances the activity of glutamate dehydrogenase and reduces the deacetylation level of MnSOD by activating SIRT3 in thyroid cancer CAL-62 and triple-negative breast cancer MDA-MB-231 cells." (PMID 38773972, 2024). "Conversely, SIRT3 can enhance the cell proliferation, invasion, and EMT of triple-negative breast cancer cells by promoting mitochondrial biogenesis and function via MnSOD activation." (PMID 38773972, 2024). "SIRT3 could be mediated by metadherin (MTDH) to enhance its activity, and enhance EMT and invasion by participating in the NFκB/SIRT3/MnSOD pathway, ultimately promoting the metastasis and spread of triple-negative breast cancer." (PMID 35832551, 2022).
viral infection (7 papers, 2016 to 2025). "To summarize, HDH ameliorates the antioxidant system induced by viral infection by activating the antioxidant proteins Sirt3 and SOD2." (PMID 39857405, 2025). "Western blot results showed that the virus infection effect was good and SIRT3 was significantly overexpressed." (PMID 39501597, 2024). "AAV8-SIRT3 KD virus infection resulted in a significant decrease of SIRT3 protein expression in the liver, whereas in heart and muscle, SIRT3 expressions were not affected." (PMID 31474877, 2019). "So far, little data is available on the involvement of SIRT3 in viral infections." (PMID 35209148, 2022). "SIRT3, SIRT4, and SIRT5 are mitochondrial deacetylases regulating a wide range of metabolic pathways that are known to be altered during viral infection as confirmed in our study." (PMID 34149631, 2021). "However, no study has thus far attempted to characterize SIRT3 substrates and the function of their site-specific acetylations during viral infection." (PMID 33857259, 2021).
acute lung injury (6 papers, 2020 to 2025). A condition of lung damage that is characterized by bilateral pulmonary infiltrates (pulmonary edema) rich in neutrophils, and in the absence of clinical heart failure. "A different study also showed that SIRT3 reduces inflammation and mitigated endotoxin-induced acute lung injury (ALI)." (PMID 36211825, 2022). "In the research of acute lung injury (ALI), SIRT3 has also been demonstrated to play a critical role in the regulation of ROS generation pro‐inflammatory response and macrophage mitochondrial bioenergetics." (PMID 39501597, 2024). "The SIRT3/LKB1/AMPK signaling pathway plays a critical role in the regulation of cellular metabolism, energy homeostasis, and stress response, including its relationship with acute lung injury (ALI)." (PMID 40635757, 2025).
head and neck cancer (6 papers, 2011 to 2023). A primary or metastatic malignant neoplasm affecting the head and neck. "At an advanced stage, oral cancer and head and neck cancer are characterized by reduced levels of mitochondrial tumor-suppressor proteins, including SIRT3 and MTUS1." (PMID 37627097, 2023). "In a study on head and neck cancer, the SIRT3 level was found to be markedly decreased in cancer tissues and was lower in advanced stages than in early stages." (PMID 37627097, 2023). "It is important to note that SIRT3 and its inhibitors are a promising new avenue to explore the development of therapies for other oral diseases, such as head and neck cancer, by inhibiting cell proliferation and promoting apoptosis." (PMID 35630070, 2022). "Our current data indicate that SIRT3 levels are elevated in head and neck cancer and that the suppression of SIRT3 levels reduces several tumorigenic parameters in vitro and in vivo." (PMID 21472714, 2011). "However, the implications of mitochondrial tumor suppressor genes SIRT3, SIRT4 and MTUS1 in head and neck cancer are largely unknown." (PMID 26785117, 2016).
intervertebral disc degeneration (6 papers, 2018 to 2025). "Very recently, SIRT3 stabilization by deubiquitinase USP11 was found to significantly ameliorate oxidative stress-induced ferroptosis in intervertebral disc degeneration, suggesting an important role of SIRT3 in mitigating ferroptosis during disease." (PMID 38395990, 2024). "The Nrf2/Sirt3 pathway promoted mitophagy, preventing nucleus pulpous apoptosis during intervertebral disc degeneration." (PMID 35938164, 2022). "Together, these findings suggest that HKL treatment upregulates the level of SIRT3 in vivo and ameliorates puncture-induced intervertebral disc degeneration in rats." (PMID 30420619, 2018). "Sirt3 activation by honokiol increases both BNIP3 and BNIP3L levels in rat nucleus pulposus cells in the pathogenesis of an intervertebral disc degeneration model." (PMID 35938164, 2022).
kidney stones (6 papers, 2020 to 2024). "A better understanding of the mechanisms relating the immune system and the underlying renal injury caused by SIRT3 knockout and CaOx inducement could provide novel insights leading to improved prediction and management of nephrolithiasis." (PMID 34849375, 2021). "The study concluded that LINC01197 inhibited the formation of kidney stones induced by calcium oxidation through the regulation of the miR-516b-5p/SIRT3/FOXO1 signaling pathway." (PMID 38397450, 2024). "Limited studies have indicated that kidney stones showed downregulated expression of SIRT3 and SIRT1." (PMID 36581622, 2022). "In a CaOx-induced nephrolithiasis model, SIRT3 has a critical role in regulating the immune system, especially in reducing inflammatory injury." (PMID 34849375, 2021). "The data indicated that SIRT3 plays a critical role in regulating the immune system, especially in reducing inflammatory injury, in the CaOx-induced nephrolithiasis model." (PMID 34849375, 2021). "This indicates that in the CaOx-induced nephrolithiasis model, SIRT3 has a critical role in regulating the immune system, especially in reducing inflammatory injury." (PMID 34849375, 2021). "A recent study found that nephrolithiasis-afflicted mice always exhibit a significant reduction in SIRT3 expression." (PMID 32724473, 2020). "Additionally, the expression of LINC01197 and Sirtuin 3 (SIRT3) was found to be dysregulated in patients with kidney stones." (PMID 38397450, 2024). "Previous studies have shown that SIRT3 could prevent oxalate damage by promoting M2 polarization of macrophages and inhibiting cell death in renal tubular epithelial cells, indicating that SIRT3 has a protective role in the pathophysiology of nephrolithiasis." (PMID 34849375, 2021). "However, regardless of SIRT3 knockout, the CaOx-induced nephrolithiasis models had a small heterogeneity of immune cell types within its samples." (PMID 34849375, 2021).
listeriosis (6 papers, 2017 to 2024). A bacterial infection caused by Listeria monocytogenes. "In agreement, SIRT3/5 deficient mice showed somewhat improved resistance to Listeria monocytogenes infection." (PMID 31632409, 2019). "Considering that SIRT3/5 deficiency increased L. monocytogenes killing by neutrophils and cytokine production by macrophages and to some extent by whole blood, we tested the relevance of these observations in vivo using a model of listeriosis." (PMID 31632409, 2019). "We next examined the contribution of SIRT3 to host defenses against bacterial pneumonia and peritonitis, listeriosis and candidiasis." (PMID 28634345, 2017). "Interestingly, SIRT3/5−/− mice resisted better than SIRT3/5+/+ mice to acute listeriosis, showing decreased signs of morbidity, reduced blood bacterial loads and significant albeit modest delayed mortality." (PMID 31632409, 2019). "As SIRT3 and SIRT5 share the similar subcellular location and targets, maybe due to their compensated functions, neither Sirt3 nor Sirt5 knockout altered host defenses against bacterial infection, but dual deficiency of SIRT3 and SIRT5 exhibited a modest protection against listeriosis host defense." (PMID 34966740, 2021). "SIRT3/5−/− mice expressed higher concentrations of cytokines but normal counts of leukocytes in blood, suggesting that the reactivity rather than the number of leukocytes protected SIRT3/5−/− mice from listeriosis." (PMID 31632409, 2019).
subarachnoid hemorrhage (6 papers, 2016 to 2023). A serious neurological disorder characterized by intracranial hemorrhage into the subarachnoid space. "In early brain injury after carotid artery puncture in rats with subarachnoid haemorrhage, SIRT3 levels decreased with increasing ROS." (PMID 37009480, 2023). "SIRT3 plays an essential neuroprotective role in subarachnoid haemorrhage; however, changes in SOD2, an important downstream molecule of SIRT3, tend to vary according to the current research." (PMID 37009480, 2023). "Taken together, our data indicate that perampanel attenuates oxidative stress and pyroptosis following subarachnoid hemorrhage via the SIRT3/FOXO3α pathway." (PMID 38044382, 2023). "Importantly, our study demonstrated for the first time in vivo that the SIRT3-FOXO3α pathway plays a neuroprotective role after subarachnoid hemorrhage, which is related to antioxidant stress and neuronal pyroptosis." (PMID 38044382, 2023). "Based on this evidence, we hypothesized that perampanel could attenuate oxidative stress and pyroptosis following subarachnoid hemorrhage via the SIRT3/FOXO3α pathway." (PMID 38044382, 2023). "It is unclear whether caloric restriction acts via the SIRT3 pathway to protect against other types of brain injury, such as subarachnoid haemorrhage." (PMID 37009480, 2023). "Similarly, puerarin, a phytoestrogen extracted from Pueraria plants, also shows anti-inflammatory and anti-apoptotic effects in early brain injury after subarachnoid haemorrhage by increasing the expression of SIRT3." (PMID 37009480, 2023). "Inflammation and apoptosis play a vital role in neurological defects after subarachnoid haemorrhage, while melatonin essentially exhibits anti-inflammatory and anti-apoptotic roles by increasing the expression of SIRT3 to alleviate early brain injury after subarachnoid haemorrhage." (PMID 37009480, 2023). "However, subsequent research revealed that the levels of both SIRT3 and SOD2 decreased following subarachnoid haemorrhage." (PMID 37009480, 2023).
vitiligo (6 papers, 2021 to 2024). Generalized well circumscribed patches of leukoderma that are generally distributed over symmetric body locations and is due to autoimmune destruction of melanocytes. "This indicates that honokiol can prevent the apoptosis of vitiligo melanocytes under oxidative stress by activating the SIRT3/OPA1 pathway, offering a novel potential avenue for the treatment of vitiligo." (PMID 39119340, 2024). "Another study looked at the expression and the activity of nicotinamide adenine dinucleotide (NAD+)-dependent deacetylase Sirtuin3 (SIRT3) in vitiligo melanocytes." (PMID 38542277, 2024). "Conversely, impaired SIRT3 in vitiligo melanocytes results in their apoptosis by inducing mitochondrial dynamic remodeling and oxidative stress." (PMID 35308171, 2022). "Specific activation of SIRT3 by honokiol was capable to protect vitiligo melanocytes against oxidative stress via the regulation of OPA-1-dependent mitochondrial dynamics." (PMID 34938344, 2021). "In addition, in a further research, the authors confirmed that SIRT3 bound directly to OPA1 and activates it by deacetylation in vitiligo melanocytes under oxidative stress, suggesting that the OPA1 is a direct target of SIRT3." (PMID 35650472, 2022).
dilated cardiomyopathy (5 papers, 2011 to 2023). Cardiomyopathy which is characterized by dilation and contractile dysfunction of the left and right ventricles. "The dilated cardiomyopathy patient with SIRT3 point mutation and reduced enzymatic activity is associated with reduced TLR9 activation and the absence of mitochondrial responses in the heart after the SGLT2 inhibitor treatment." (PMID 33138323, 2020). "Moreover, SIRT3 prevents DOX-induced dilated cardiomyopathy by modulating protein acetylation and oxidative stress." (PMID 36691640, 2023). "Finally, we investigated the SIRT3-dependent mitochondrial increases of TLR9 by empagliflozin in subjects with dilated cardiomyopathy (DCM)." (PMID 33138323, 2020). "Indeed, dysregulation of the mitochondrial deacetylase SIRT3 is already known to drive pathological states such as dilated cardiomyopathy and tumorigenesis in mice." (PMID 21858060, 2011).